BRAF (B-Raf proto-oncogene, serine/threonine kinase)
Diseases named in the same sentence as BRAF in open-access papers (continued):
Sharing a sentence is not in itself a finding about the gene and the disease.
cancer (continued). "Moreover, recent studies have shown that SHP2 inhibitors were effective in bypassing paradoxical activation of MAPK signaling upon BRAF inhibition in RAS-mutant cancers." (PMID 31426419, 2019). "In the cited study, even if the WNT pathway was notably activated in dysplastic serrated lesions and BRAF mutant cancers, it was not due to truncating APC mutations, suggesting the existence of alternative mechanisms of activation of the WNT signaling." (PMID 31330830, 2019). "Interestingly, the JAK1/2 inhibitor enhanced the growth inhibitory effect of the MEK-inhibitor, particularly in poorly immunogenic BRAF or KRAS mutant cancer cells (HT29 and SW620)." (PMID 30670049, 2019). "Likewise, PAX8 knockdown also harbored LDR-mediated suppression of BRAF-induced cellular transformation in 850-5C cancer cells as observed by sphere forming and soft agar colony forming assays." (PMID 30760304, 2019). "Here, we have demonstrated a comprehensive characterization of a drug-resistant model including various mechanisms of resistance, such as upregulation of up- and downstream effectors of BRAF, acquisition of cancer stem-like traits, and elevated invasive and proteolytic activities." (PMID 31877948, 2019). "The risk of developing a secondary cancer and mainly the lack of efficacy in BRAF-wild type tumors clearly support the contraindication of both Vemurafenib and Dabrafenib in patients with BRAF-wild type cancers." (PMID 31762942, 2019). "Immunotherapy is currently regarded as the future for cancer cure, and in this view targeting the chemokine/chemokine receptor system might represent a new frontier for the use of BRAF inhibitor drugs." (PMID 31762942, 2019). "BRAF mutant cancers may be particularly sensitive to autophagy inhibition when combined with BRAF inhibition (BRAFi) as autophagy can be induced as a survival mechanism, potentially limiting drug efficacy." (PMID 31515514, 2019). "Nevertheless, a detailed understanding of these mechanisms in BRAF-mutant tumors could be key to increasing the efficacy of MAPK-targeted therapies in these cancers." (PMID 31581557, 2019). "However, the efficacy of MEK inhibitors as single agents is relatively modest, whereas the combination of BRAF and MEK inhibitors in BRAF-mutant cancers has shown great success." (PMID 31426419, 2019). "These cancers are recommended to be treated with BRAF inhibitor combined with MEK inhibitors." (PMID 30800219, 2019). "Targeting ERK1/2 could be valuable for therapy-resistant cancer to known clinically used BRAF and MEK inhibitors." (PMID 31709177, 2019). "Targeted inactivation of BRAF and similar driver oncogenes, which are often protein kinases, by pharmacologic inhibitors is an archetypal example of targeted therapeutic intervention in cancers." (PMID 31426419, 2019). "As the Ras pathway is heavily mutated in cancer, we next set to explore whether TRF1 is also a direct substrate of different kinases of the Ras pathway—including ERK, MEK, and bRaf kinases." (PMID 31273934, 2019). "Additional BRAF mutations in exons 11 and 14 were reported in human cancers, but until now, not in dogs." (PMID 30893857, 2019). "MED12 mutations were mutually exclusive to cancers with TERT promoter mutations and BRAF p.V600E." (PMID 31835496, 2019). "Interestingly, re-expression of TERT has been shown to promote escape from OIS in BRAF-mutant cancer cells." (PMID 31391125, 2019). "Future interesting applications of EACCD could include studying molecular markers, such as T1799A point BRAF mutation, TERT mutation, and HRAS mutation as these become available in cancer registries." (PMID 31139148, 2019). "Among all the observed variants in the 585 cancer genes annotated in OncoKB16, a repository of curated cancer genes, IDH1 R132H and BRAF V600E are the two most tissue-specific variants with NMIs of 0.18 and 0.13, respectively, followed by GTF21 L424H with an NMI of 0.08." (PMID 31796730, 2019).
cancer (continued). "Clinically, the BRAF mutant/MSS cancers are similar to the BRAF mutant/MSI cancers as they frequently occur in the proximal colon but also resemble BRAF wild-type cancers in terms of equal gender distribution and a younger age of onset and they more commonly present at advanced stages." (PMID 30598662, 2018). "As such, the FDA has approved BRAF inhibitors for cancer treatment." (PMID 29565994, 2018). "However, reports of stage II BRAF mutant/MSS cancers having shorter survival rates than BRAF wild-type/MSS cancers suggests that the former have a higher risk of relapse." (PMID 30598662, 2018). "The BRAF-V600 study is a trial comprising multiple sub-studies to evaluate the efficacy of vemurafenib for non-melanoma BRAF V600E mutation-positive cancers." (PMID 30182068, 2018). "The oncogenic role of BRAF pseudogene in cancer comes from a study with animal models." (PMID 30071685, 2018). "Of the remaining 17 variants, all but three are accounted for by six genes (BRAF, CBL, MAP2K1, MAP2K2, RAF1, and SOS1) encoding members of the RAS-MAPK pathway, among which nine variants have previously been reported in either congenital disorders or cancer." (PMID 30355600, 2018). "Therefore, identifying other BRAF inhibitors that act as dual inhibitors of BRAF/CRAF is of key importance for cancer research." (PMID 29565994, 2018). "Early-stage BRAF mutant/MSI cancers have an activated immune profile with lymphocytic infiltration which could be causal to their good prognosis." (PMID 30598662, 2018). "A recent study of 200 TSAs found that all lesions retained MLH1 expression which associates with an MSS phenotype and therefore indicates TSAs may progress to BRAF mutant/MSS cancers." (PMID 30598662, 2018). "AZ304 may constitute a novel drug for the treatment of BRAF mutant and wild type human cancers, alone and/or in combination with Cetuximab." (PMID 29755114, 2018). "Therefore, it is possible that miR-550a-3-5p exerts direct inhibition of oncogenic YAP and subsequently perturbs the PI3K/AKT pathway in BRAF mutant cancer cells." (PMID 29844307, 2018). "The BRAF mutation is most closely associated with the serrated neoplastic pathway in which a serrated type polyp, either a sessile serrated adenoma (SSA) or a traditional serrated adenoma (TSA), acquires defined molecular aberrations leading to cancer." (PMID 30598662, 2018). "There are two types of serrated polyp from which BRAF mutant cancers arise." (PMID 29304767, 2018). "One strategy to target cancer specific proteins is with inhibitors that target the mutant variant of the protein: drugs such as gefitinib (against mutant EGFR) and vemurafenib (against BRAF V600E) have a good degree of success in cancer management." (PMID 30150714, 2018). "Importantly, the combination treatments were effective against BRAF wild type cancer cells potentially expanding the clinical reach of BRAFi’s." (PMID 29568360, 2018). "This is in line with a recent publication which concluded that BMS-906024 not only sensitizes NSCLC to paclitaxel, but that this occurs more potently in KRAS and BRAF wildtype cancers therefore, possibly being able to predict better patient outcomes to dual combination therapy." (PMID 30464927, 2018). "BRAF gain-of-function mutations and AXL overexpression, which are both observed in various cancers at high frequencies, are important therapeutic targets for the treatment of cancers." (PMID 30157175, 2018). "Poorer survival has been associated with peritoneal spread which may reflect more the propensity of aggressive BRAF mutant cancers to metastasize to this region." (PMID 30598662, 2018). "Additionally, non-V600 mutant cancers were associated with more favourable overall survival rates compared to both BRAF V600 mutant and wild-type cancers." (PMID 30598662, 2018).
cancer (continued). "This may further highlight the relevance of screening for presence of a BRAF mutation and considering a more aggressive treatment strategy for stage II BRAF mutant/MSS cancers to reduce their associated survival risk." (PMID 30598662, 2018). "The frequency of late-stage MSI cancers is lower than MSS cancers which reflects the lower metastatic risk of MSI cancers, however the prognostic benefit conferred by MSI was lost in the metastatic setting where BRAF mutant/MSI cancers had similarly poor survival rates as BRAF mutant/MSS cancers." (PMID 30598662, 2018). "It is likely that NEK9 and CDK16 inhibition may contribute to the activity of dabrafenib, perhaps suggesting utility of this drug in other, non‐BRAF‐mutant cancers." (PMID 29112787, 2018). "Given that functional evidence pointed to continued activation of the MAPK pathway as a way cancer cells exploit to overcome the roadblock imposed by BRAF inhibitors, combining BRAF and MEK inhibitors resulted in improved clinical outcomes compared to single agent BRAF-directed therapy." (PMID 30558661, 2018). "Also highlighted are the functional consequences of aberrant splice variants (BCR-Abl35INS, BIM-γ, IK6, p61 BRAF V600E, CD19-∆2, AR-V7 and PIK3CD-S) in promoting resistance to cancer targeted therapy or immunotherapy." (PMID 30463359, 2018). "Overcoming this resistance may hold the key to novel therapies for the treatment of this cancer entity and may also be feasible in tumors resistant to currently used mutant BRAF inhibitors." (PMID 29624862, 2018). "Furthermore, AZ304 markedly inhibited cell proliferation in mutant BRAF cancer cell lines, and effectively reduced cell growth in selected cell lines harbouring wild type BRAF/RAS or mutant RAS." (PMID 29755114, 2018). "Although selective BRAF mutant inhibitors have been developed, such as vemurafenib and dabrafenib, acquired or intrinsic drug resistance is a major problem for the treatment of BRAF-mutant cancer patients." (PMID 29844307, 2018). "Due to the importance of BRAF overactivation in cancer, we next focused on this oncogene." (PMID 30157175, 2018). "We next investigated whether BRAF V600E and TERT promoter mutations cooperatively affected TERT expression in a panel of human cancer cells with various BRAF and TERT genotypes." (PMID 29422527, 2018). "Overactivation of BRAF is observed in a vast majority of cancers." (PMID 30157175, 2018). "Our group has previously shown that a loss of CDX2 is specific for BRAF mutation and for the CIMP-high phenotype and that both MSI and MSS cancers may show loss of CDX2 in this context." (PMID 30257705, 2018). "However, a recent study that stratified a large cohort of stage III cancers for MMR status and BRAF and KRAS mutations found that MSS cancers with a BRAF mutation had a similarly poor 5-year survival rate as MSS cancers with a KRAS mutation." (PMID 30598662, 2018). "The BRAF mutant serrated pathway rarely mutates APC in this manner; however, activation of the Wnt pathway can occur through alternative mechanisms as nuclear beta-catenin is evident in approximately half of the serrated dysplastic polyps and cancers studied." (PMID 30598662, 2018). "Moreover, BRAF overactivating mutations are potential predictors/biomarkers for loss of RIPK3 expression and necroptosis resistance in cancer." (PMID 30157175, 2018). "In conclusion, there are two types of serrated polyps from which BRAF mutant cancers arise." (PMID 29652830, 2018).
cancer (continued). "The differences in the compartmentalisation of GFP-tagged, N-terminally truncated as opposed to full-length BRAF is also interesting and potentially has implications for cancers bearing single nucleotide variants as opposed to structural variants of BRAF." (PMID 30603699, 2018). "BRAF mutations confer a relatively poor survival, but this phenomenon is restricted to carcinomas not showing MSI." (PMID 30360391, 2018). "Interestingly the BRAF-V600E positive TSA and carcinoma samples (both also containing mutation in the APC gene) clustered closely with SSP, but not FAP or other sample types." (PMID 29590112, 2018). "Both GEC alone and GEC + BRAF mutation analysis, therefore, appear to be not reliable for cancer detection (worst rule-in tests)." (PMID 28472764, 2017). "However, patients tended to have co-existence of alterations in well-known cancer-related genes (for example, BRAF and MLL2) in these malignant tumours, which is distinct from benign nodules." (PMID 28580939, 2017). "The knowledge of these metabolic finding of BRAF-driven cancers may raise additional researches and questions postulating that somatic mutations induce organ-specific molecular mechanisms enabling different prognostic prediction in different cancers." (PMID 27738305, 2017). "Among non-MSI-high cases, BRAF mutation was the most distinct marker that was strongly correlated with other markers in the proximal cancer network (degree = 10), but not in the distal cancer network (degree = 3) (Cook’s distance = 0.17)." (PMID 28623901, 2017). "Mutations in BRAF and KRAS, acting in the RAS-RAF-MAPK kinase cascade and mutated PIK3CA, acting in PI3K-PTEN-AKT signaling pathway, are known for their contribution to the development of CRC and are associated with cancer prognosis." (PMID 28125730, 2017). "In the present study, almost all HVPTC cases (16/17, 94.1%) harbored a BRAF V600E mutation, which indicated that BRAF mutation is quite often in HVPTC and might play an important role in its carcinogenesis and cancer progression." (PMID 28423545, 2017). "Notably, we observed that methylation of DKK1 is high in BRAF mutant and CIMP (CpG island methylator phenotype)-positive cancers, whereas AXIN2 methylation appears to be associated with CMS4." (PMID 28368388, 2017). "Patients with ‘stroma-rich’ tumors have poorer clinical outcomes because stromal cells provide growth and metabolic factors that protect cancer cells from a variety of anti-cancer drugs, including chemotherapeutic agents and targeted drugs such as BRAF inhibitors." (PMID 28653584, 2017). "The BRAF protein kinase is widely studied as a cancer driver and therapeutic target." (PMID 28454577, 2017). "Therefore, members of MAPK/ERK pathways, particularly RAS and BRAF are potential drug targets, the inhibition of which is a strategy for developing cancer treatment." (PMID 27965461, 2017). "The use of single agent BRAF inhibitor significantly increased the risk of developing cuSCC comparing with dual BRAF/MEK inhibitors for all-grade (RR 4.72, 95% CI: 2.42–9.20) and high-grade (RR 4.92, 95% CI: 2.64–9.16) in cancer patients." (PMID 29137342, 2017). "Overall, these results suggest that while trametinib is a potent MEKi and would be effective for BRAF-fusion expressing PLGGs and adult cancers with similar BRAF-fusions, we require a deeper understanding of emergent resistance mechanisms and targeting of alternative pathways." (PMID 29156677, 2017).
cancer (continued). "Most of the components in the RAS/ERK signaling pathway are overexpressed in the breast, but, in most cases their overexpression has not been related to activating mutation of either RAS or BRAF, as happens in other types of cancers, such as melanoma." (PMID 28241486, 2017). "Limiting the paradoxical reactivation in BRAF wild-type cancers, as well as potentially limiting the side effects in skin of BRAF inhibitors, may provide therapeutic benefit for many patients." (PMID 28431544, 2017). "Even for genes that were significant in MutSigCV, oncodomain hotspots are more sensitive as they identify those same genes as significant in more cancer types for which they are known to play a role like BRAF in STAD, GBM, and UCEC and EGFR in COAD, STAD, and SKCM." (PMID 28426665, 2017). "The cancer biomarker panel status was associated with neither microsatellite instability (MSI) status nor BRAF mutation status, although all cancers negative for the biomarker panel (n = 4) were MSS and had no BRAF V600E hotspot mutation." (PMID 28878843, 2017). "The BRAF‐selective inhibitor PLX4720 also combined with ABT‐737/263 in BRAF‐mutant cancer cells." (PMID 28548464, 2017). "Moreover, many studies have investigated multifocal PTC clonality through a number of approaches, including X-chromosome inactivation, BRAF mutation, RET rearrangements, loss of heterozygosity, or allelic imbalances of distinct cancer foci." (PMID 28302162, 2017). "BRAF V600E mutation testing has a high specificity for malignancy, but its sensitivity is too low to rule out cancer reliably." (PMID 29085338, 2017). "Approximately two-thirds of human cancers, including skin, colon, lung, and pancreas; multiple myeloma; and hairy cell leukemia, have aberrations in the ERK1/2 cascade, largely due to activating mutations in signaling intermediates such as EGFR, KRAS, or BRAF." (PMID 28982763, 2017). "In many human cancers, dysregulation of the MAPK pathway is caused by a mutation in the BRAF gene." (PMID 28915798, 2017). "Together, these findings highlight the prevalence of pan-cancer BRAF-fusions." (PMID 29156677, 2017). "In BRAF wild type cancers with nuclear β-catenin staining, 19/27 (70.4%) showed a concomitant increase in RNF43 cytoplasmic expression, which may represent a futile attempt to dampen the Wnt signal by RNF43-mediated degradation of the Frizzled receptor." (PMID 27661107, 2016). "This high rate was verified in a second series of 25/35(71%) BRAF mutant/MSI cancers." (PMID 27661107, 2016). "In a recent phase II “basket” study of vemurafenib in BRAF V600 mutated non-melanoma cancers, one patient with CCA achieved a durable PR of more than one year." (PMID 27102149, 2016). "BRAF mutant cells often harbor aberrations in other cancer signaling pathways, and our analysis suggests that other genes may also contribute to the sensitivity of BRAF mutant cells to BRAF inhibitors and MEK inhibitors." (PMID 26916442, 2016). "Thus, there is a need to identify and analyze the adaptations that can be deployed rapidly by cancer cells and that enable survival and the resumption of proliferation in spite of inhibition of mutant BRAF." (PMID 26673621, 2016). "Since IL-2- and IL-15- pre-activated NK cells may be used in protocols of adoptive immunotherapy in cancer patients, we further investigated the effect of BRAF-i and MEK-i on NK cells that had been pre-activated for 2 days with IL-2 or IL-15." (PMID 27563819, 2016).